INS (insulin)
Diseases named in the same sentence as INS in open-access papers (continued):
Sharing a sentence is not in itself a finding about the gene and the disease.
Insulin resistance (continued). "This suggests there may be a threshold past which greater underlying insulin resistance or β-cell function is exponentially associated with greater intervention-induced reductions in postprandial insulin." (PMID 33308235, 2020). "At the same time, the increase in insulin was associated with moderate concentrations of glucose triggering a peripheral insulin resistance status which could contribute to raise NEFA levels." (PMID 33143190, 2020). "Moreover, pubertal insulin resistance is physiological, occurring with pubertal progression and resolving by the end of puberty, and is associated with decreased peripheral insulin sensitivity and increased insulin secretion." (PMID 33171633, 2020). "Indeed, hepatic steatosis is associated with insulin resistance, whereas increased beta-oxidation results in hepatic sensitivity to insulin." (PMID 32128655, 2020). "Insulin resistance is well known as an essential feature of T3D, therefore treatment strategies for T3D, particularly those aimed at improving insulin sensitivity, may also benefit those patients at risk for AD at the early stages." (PMID 32365816, 2020). "The infusion of lipids in insulin sensitive subjects temporarily causes lipid-induced insulin resistance and metabolic inflexibility, which is therefore a well-appreciated model to investigate the mechanisms underlying the development of insulin resistance and metabolic inflexibility." (PMID 32976523, 2020). "Typically, reduced insulin signaling is a hallmark of insulin resistance." (PMID 33184414, 2020). "In addition, DAGs are incorporated into lipid droplets but have also been implicated in affecting the insulin signaling cascade in insulin resistance." (PMID 32272236, 2020). "Additionally, chronic low‐grade inflammation in adipose tissue impairs insulin signaling, which further stimulates expression of genes encoding proteins involved in insulin resistance." (PMID 32537767, 2020). "A case cohort study in 2017 found that higher insulin levels and insulin resistance may increase the risk of lung cancer." (PMID 33250766, 2020). "In addition to decreased insulin sensitivity in metabolic tissues, aging is also associated with vascular insulin resistance." (PMID 32503213, 2020). "Similarly, in this study, an increase in GLUT4 expression, glucose uptake and the glycogen content in skeletal muscle was observed, suggesting that increased insulin compensated for skeletal muscle insulin resistance caused by glucocorticoids." (PMID 32647998, 2020). "These researchers claimed that hepatic insulin resistance could be attributed to the increase of hepatic triglycerides and diacylglycerol content which may cause reduced insulin signalling through activation of PKC." (PMID 32670384, 2020). "Bacterial translocation might be an interesting concept to explain inflammatory changes in obese and diabetic tissues that leads into insulin activity loss (beta-cell dysfunction and insulin resistance)." (PMID 33178196, 2020). "Our results demonstrate that both higher ppBMI and GWG increase the risk of offspring's insulin resistance, but the effect of ppBMI on insulin sensitivity in offspring may develop as consequence of their adiposity." (PMID 32567808, 2020). "Impaired insulin signaling is a hallmark of insulin resistance." (PMID 30761259, 2019). "As elevated insulin levels promote oxidative stress, the insulin resistance observed in SIRD may in part be caused by elevated peripheral oxidative stress." (PMID 30837889, 2019). "Taken together, the plasticity of the methylome of monocytes under the insulin-resistant condition may be contributing to the variability of systemic levels of inflammation underlying insulin resistance." (PMID 31253200, 2019).
Insulin resistance (continued). "Since systemic glucose metabolism converges in mitochondria due to insulin signalling required for normal mitochondrial function, it is clear that an impairment of this metabolic function during insulin resistance may be the causal in disease progression." (PMID 30803440, 2019). "In addition, evidence from mouse models have supported that a deficiency of genes involved in insulin-mediated signals result in insulin resistance and glucose intolerance." (PMID 30642126, 2019). "Also, the G7G genotype of TNF-alpha 308 G/A polymorphism increases insulin levels and insulin resistance among women with gestational diabetes." (PMID 31828161, 2019). "Insulin and glucose measurements were included to assess the possible role of reduced nutrient access to the bone as a cause of low diabetic bone quality, as the measurements allow assessment of insulin resistance in meal-tolerance tests." (PMID 31261978, 2019). "Thus, in mice, hepatocyte-specific overexpression of Dpp4 is associated with hepatic insulin resistance and liver steatosis, whereas knockdown of Dpp4 results in improved insulin sensitivity and reduced lipid accumulation in cultured hepatocytes." (PMID 30828317, 2019). "The cardiometabolic risk markers (glucose, lipids, insulin, the insulin resistance/sensitivity indexes, leptin and Hcy) studied according to the n-6/n-3 classification, confirm that this vegetarian population exhibits a low cardiometabolic risk, in agreement with other authors." (PMID 31330792, 2019). "The reduced response to insulin causes pancreatic β-cells to increase insulin secretion, leading to a state of chronic hyperinsulinemia, which was found to be a result and driver of insulin resistance." (PMID 31234331, 2019). "Additionally, disordered liver and adipose tissue lipolysis can elevate fatty acid flux to liver and further deteriorate hepatic lipid accumulation, which significantly impair insulin signal pathway and cause hepatic insulin resistance." (PMID 31649547, 2019). "Glutamate excitotoxicity has been observed in numerous diseases, such as ischemic stroke, traumatic brain injury, and Alzheimer’s disease, for which insulin resistance has been shown to be a risk factor or a symptom, and intranasal insulin has been shown to be a promising treatment." (PMID 31611766, 2019). "Mechanistically, given that glucose uptake and utilization in the brain and neuronal cells are stimulated by insulin, insulin deficiency or insulin resistance could disturb energy metabolism and thus contribute to the pathogenesis of AD." (PMID 31507407, 2019). "In conclusion, the short-term insulin exposure in our experiments was evidently a protective treatment against excitotoxicity, in a sharp contrast to chronic insulin exposure causal to neuronal insulin resistance, the adverse factor in excitotoxicity." (PMID 31611766, 2019). "There is a long-standing idea that insulin resistance and systemic adiposity increase the risk of cardiovascular (CV) events, however a new school of thought is emerging that defines myocardial insulin resistance as a defense against glucotoxicity and oxidative stress." (PMID 31440740, 2019). "In addition, TLR2-deficient mice are protected from HFD-induced adiposity, insulin resistance, impaired insulin secretion, and hypercholesterolemia." (PMID 31582899, 2019). "Loss of Tmem127 enhances insulin sensitivity and protects from diet-induced insulin resistance likely due to reduced hepatic gluconeogenesis and increased glucose clearance in fat tissue, although other mechanisms may also be involved." (PMID 31624249, 2019). "The mechanisms underlying the development of insulin resistance are not fully understood and may occur at many levels of insulin signalling." (PMID 31478094, 2019).
Insulin resistance (continued). "The metabolic etiology of AN has been suggested by the identification of significant genetic correlations between AN-associated variants and various metabolic features (e.g., insulin, insulin resistance, type II diabetes, and obesity) in recent consortium studies." (PMID 31540208, 2019). "Abnormally accumulated visceral fat is a risk factor for insulin resistance, which can reduce insulin sensitivity, increase the expression and secretion of proinflammatory cytokines in adipose tissue and promote the development of DM and cardiovascular diseases." (PMID 30630489, 2019). "To date, only one longitudinal study has examined the bidirectional relationship between inflammation and insulin resistance and showed that baseline levels of hsCRP and interleukin-6 were positively associated with subsequent increases in fasting insulin, HOMA-IR, and beta-cell function." (PMID 31443647, 2019). "Similar to a previous report, 5αR1KO HFD mice were predisposed to develop insulin resistance, with a trend toward a higher fasting insulin level and an increased insulin response to a glucose challenge compared with wild-type HFD mice, irrespective of the presence of A-348331." (PMID 31199473, 2019). "Elevated iron stores cause insulin resistance and possibly defective secretion of insulin." (PMID 30847229, 2019). "Moreover, plasma from obese children caused insulin resistance by impairing insulin-stimulated NO production, a characteristic of endothelial dysfunction, in HUVECs with concomitant activation of ER stress response." (PMID 30987118, 2019). "Type 2 diabetes is associated with impaired insulin secretion and insulin resistance." (PMID 30764536, 2019). "Here, we investigate the hypothesis that MOTS‐c alters plasma metabolites, which are associated with insulin resistance, to improve insulin sensitivity." (PMID 31293078, 2019). "Acromegaly is a unique condition of concomitant increases in GH, IGF-I, and insulin concentrations, where the increase in insulin resistance, paradoxically, is associated with reduced total body fat and even reduced fat accumulation in metabolic organs such as the liver." (PMID 31417493, 2019). "Since we did not observe any significant difference in HOMA-IR, a marker for insulin resistance, a deficient insulin secretion could explain the high fasting glucose in those born SGA." (PMID 31002705, 2019). "Socs3 tissue-specific deficiency in liver and skeletal muscle could enhance insulin sensitivity and protect against obesity-associated insulin resistance." (PMID 31333621, 2019). "Furthermore, investigations also reveal that insulin resistance in neurons promotes the phosphorylation level of tau, and in turn hyperphosphorylation of tau also causes dysfunctional insulin signaling." (PMID 31275224, 2019). "Cortisolcan affect insulin production and glucose metabolism and it can cause insulin resistance." (PMID 31340612, 2019). "Our data are consistent with recent findings whereby reduced insulin clearance was identified as an early adaption to impaired SI, a response likely important for preserving beta cell function by minimising the insulin secretory burden associated with insulin resistance." (PMID 31489455, 2019). "Dietary habits that continually expose to post-meal hyperglycemia are believed to impair first-phase insulin secretion and decrease insulin sensitivity that might contribute an increased risk for insulin resistance and type 2 diabetes development." (PMID 31737676, 2019). "Thus, obesity results in damage to insulin signaling pathways, deficiencies in neuroplasticity, and insulin resistance, which then leads to type-II diabetes in the periphery and Alzheimer’s disease, which has been called type-III diabetes, in the CNS." (PMID 31311133, 2019). "Furthermore, DPP4 activity was associated with all insulin resistance markers herein tested (i.e., we found direct associations with fasting insulin and HOMA-IR and inverse associations with SHBG and QUICKI)." (PMID 30886868, 2019).
Insulin resistance (continued). "Moreover, the acquisition of insulin resistance that accompanies normal pregnancy is linked to changes insulin signalling components in the skeletal muscle and WAT." (PMID 31466137, 2019). "Previous studies have suggested that GDM is caused by enhanced insulin resistance and pancreatic beta (β)-cell dysfunction, involving genes that are related to insulin signaling, insulin secretion, maturity-onset diabetes of the young, and lipid and glucose metabolism, to name a few." (PMID 31783860, 2019). "This concept is consistent with the idea that triglyceride content itself is not casually involved in insulin resistance and has prompted several efforts to identify the lipid intermediates responsible for causing insulin resistance or preserving the insulin sensitivity of athletes." (PMID 31048405, 2019). "Deeper understanding of vitamin D molecular involvement in processes related to insulin signaling may result in new therapeutic strategies preventing from development of insulin-resistance-associated disorders." (PMID 30959886, 2019). "However, when β-cell function decreases, insulin production is inadequate to overcome insulin resistance, causing the blood glucose level to rise, leading to T2D." (PMID 30759846, 2019). "Sodium has been demonised as the cause of hypertension when perhaps insulin and insulin resistance may actually be the culprits." (PMID 31357547, 2019). "Thus, while amylin overexpression drives the development of insulin resistance and increased insulin secretion, amylin secretion itself is also linked to the level of insulin secretion." (PMID 31601900, 2019). "This may be due to the progressive loss of β-cells causing impaired insulin secretion and increasing insulin resistance." (PMID 31938590, 2019). "It is possible that iron overload in the liver may cause insulin resistance by decreasing the inhibiting effect of insulin on hepatic glucose production." (PMID 31969861, 2019). "Insulin signaling and iron metabolism are interconnected, as high tissue iron stores are associated with insulin resistance, and conversely, impaired insulin signaling may lead to iron accumulation in an affected tissue." (PMID 30949015, 2019). "This apparent insulin resistance may be caused by the high concentration of insulin (3 μM) used in the maintenance medium, resulting in down-regulation of insulin receptor expression at the plasma membrane." (PMID 30948643, 2019). "Stress has an effect on glucose metabolism through the activities of hypothalamic-pituitary-adrenal (HPA) axis as its chronic activation and joint mechanisms affect insulin activities and may cause insulin resistance and β-cell dysfunction." (PMID 31803711, 2019). "Moreover, insulin resistance and a reduced anabolic action of insulin has been related to adiposity and to loss of muscular strength." (PMID 30795629, 2019). "The main characteristic of DM is hyperglycemia that results from either an autoimmune destruction of pancreatic β-cells and, thus, loss of insulin secretion (type 1 diabetes, T1DM) or insulin resistance and variable degrees of inadequate insulin secretion (type 2 diabetes, T2DM)." (PMID 31506549, 2019). "In the glucose absorption assay, phytosterol exhibited a marked improvement in insulin-induced glucose absorption, which might be associated with improved insulin resistance." (PMID 31340583, 2019). "GDM was associated with insulin resistance and insulin-signaling system may require ADCYAP1 participation." (PMID 31485258, 2019). "Although normal variations in insulin-response appear to drive normal variations in adiposity: this does not negate the considerable evidence that clearly shows that increases in adiposity cause insulin resistance." (PMID 30809194, 2019). "Future studies may include a well-powered randomized controlled trial of maternal DHA and/or vitamin D supplementation in women at risk for insulin resistance in order to augment insulin sensitivity." (PMID 31783739, 2019).
Insulin resistance (continued). "We hypothesized that the increased insulin exposure caused by aggravated insulin resistance in HFD mice may induce TGF-β1 excretion from the respiratory epithelium." (PMID 31133649, 2019). "Altogether, insulin resistance was associated with higher inflammation and altered lipid metabolism, which might cause insulin-resistant participants to have impaired responses to additional stresses 19 and below." (PMID 31142858, 2019). "Since insulin resistance is a common feature of obesity, resulting in abnormally high levels of circulating insulin, this could also account for the increased risk of respiratory problems." (PMID 31133649, 2019). "In the present study, we tested whether a decrease in circulating FFA and long-chain acylcarnitine concentrations after glucose administration in a GTT is associated with insulin sensitivity and can be used for the diagnosis of insulin resistance." (PMID 31920980, 2019). "Furthermore, studies have demonstrated that obesity-induced insulin resistance and type 2 diabetes are associated with altered gene expression of insulin signaling genes." (PMID 31226166, 2019). "Since many studies have reported that oxidative stress can cause insulin resistance by modulating lipotoxicity, we sought to evaluate whether antioxidants could have a beneficial role in our adipocyte-specific insulin-resistant model." (PMID 31309261, 2019). "Moreover, it was reported that reduction in the levels of insulin and AUCglucose is associated with improving insulin resistance." (PMID 31998245, 2019). "To clarify further the inhibitory mechanism of the insulin signaling by the mantle extract, we investigated mRNA expression levels of ER stress‐induced genes (Samali, FitzGerald, Deegan, & Gupta, 2010), which have been reported to causes insulin resistance." (PMID 31289664, 2019). "The increased risk of T2D amongst South Asians is closely associated with the presence of insulin resistance and related metabolic disturbances (raised fasting insulin and glucose, central adiposity, high triglycerides and low high density lipid [HDL] cholesterol)." (PMID 31063476, 2019). "Taking into account the clinical observation that treatment with insulin is able to overcome statin-associated insulin resistance and the results of the current study, impaired activation of Akt appears to be the more likely reason for insulin resistance than ER stress." (PMID 31092879, 2019). "In addition, mutations in IR and in insulin signaling molecules genes have been associated with insulin resistance." (PMID 31027340, 2019). "As the main tissue involved in insulin-stimulated glucose uptake, insulin resistance and hyperglycemia associated with SGA medication may be generated in the skeletal muscle." (PMID 31671770, 2019). "This pilot data has identified phospholipid metabolites as potential novel biomarkers of obesity-associated insulin sensitivity and confirmed the association of known metabolites with increased risk of obesity-associated insulin resistance, with possible diagnostic and therapeutic applications." (PMID 31640727, 2019). "Insulin resistance in these patients might not only increase insulin demand, but also the risk for cardiometabolic complications." (PMID 30617710, 2019). "SHORT syndrome is an autosomal dominant condition associated severe insulin resistance (IR) and lipoatrophy due to post-receptor defect in insulin signaling involving phosphoinositide-3-kinase regulatory subunit 1 (PIK3R1), where no clear treatment guidelines are available." (PMID 31583022, 2019). "Insulin resistance and insulin secretion defect are the two most recognized causes of T2DM." (PMID 31013790, 2019). "Further, it was recently found in rat hepatoma cells that persistent high insulin levels are associated with a persistent alteration at the insulin receptor tyrosine kinase domain, which may act to initiate or progressively worsen insulin resistance." (PMID 31141900, 2019).